GFPT2 (glutamine--fructose-6-phosphate transaminase 2)
Description:
Rate-limiting enzyme of the hexosamine biosynthetic pathway (HBP) that catalyzes the formation of glucosamine-6-phosphate from fructose-6-phosphate and glutamine, thereby controlling the flux of glucose into this pathway. Via control of the HPB, likely regulates the availability of precursors for N- and O-linked protein glycosylation (By similarity). Exhibits feedback inhibition by UDP-N-acetylglucosamine (UDP-GlcNAc), although to a lesser extent than GFPT1.
Synonyms: GFAT 2; GFAT2; GFAT
Tractability: PROTAC: ubiquitination databases record sites on it.
Gene: Protein-coding gene on chromosome 5 (180,300,682 to 180,353,339, reverse strand). Ensembl gene ENSG00000131459.
Subcellular location (Human Protein Atlas): Vesicles
Pathways (Reactome):
Metabolism of proteins: Synthesis of UDP-N-acetyl-glucosamine
Gene Ontology:
Molecular function: glutamine-fructose-6-phosphate transaminase (isomerizing) activity; protein binding; carbohydrate derivative binding
Biological process: fructose 6-phosphate metabolic process; UDP-N-acetylglucosamine biosynthetic process; energy reserve metabolic process; carbohydrate derivative biosynthetic process; carbohydrate derivative metabolic process
Cellular component: cytosol
Genetic constraint (gnomAD): Loss-of-function variants: 39 observed, 45.26 expected, observed/expected ratio (o/e) 0.86, 90% interval 0.67 to 1.13. The upper end of that interval is the gene's LOEUF score, 1.13, which puts it in group 4 of 6, group 1 being the genes least tolerant of losing a copy. Missense variants: 467 observed, 532.41 expected, observed/expected ratio (o/e) 0.88, 90% interval 0.81 to 0.95. Synonymous variants: 226 observed, 214.69 expected, observed/expected ratio (o/e) 1.05, 90% interval 0.94 to 1.17.
Homologues: Orthologues: chimpanzee GFPT2 (99% identical), macaque GFPT2 (99% identical), guinea pig GFPT2 (98% identical), pig GFPT2 (98% identical), mouse Gfpt2 (98% identical), dog GFPT2 (98% identical), rat Gfpt2 (98% identical), rabbit GFPT2 (98% identical), tropical clawed frog gfpt2 (83% identical), zebrafish gfpt2 (78% identical), Drosophila melanogaster Gfat2 (67% identical), Drosophila melanogaster Gfat1 (65% identical). Paralogues in human: GFPT1 (79% identical).
Diseases named in the same sentence as GFPT2 in open-access papers:
GFPT2 is named in the same sentence as 51 diseases in open-access papers, as found by Europe PMC text mining. Sharing a sentence is not in itself a finding about the gene and the disease. The quoted sentences say what the papers report.
breast carcinoma (9 papers, 2020 to 2025). "The mRNA level of glutamine‐fructose‐6‐phosphate transaminase 2 (GFPT2) is upregulated in many cancers, such as glioblastoma, lung adenocarcinoma and breast cancer." (PMID 40903893, 2025). "We then compared GFPT2 expression across clinical breast cancer subtypes and breast cancer cell lines and knocked down GFPT2 to assess its effects on the EMT program, cell growth, and cell invasion in the D492 EMT model." (PMID 34923141, 2022). "We then identified the hexosamine biosynthesis pathway (HBP) rate-limiting enzyme, glutamine-fructose-6-phosphate transaminase 2 (GFPT2), as a potential target in claudin-low breast cancer progression." (PMID 34923141, 2022). "Our results demonstrate that GFPT2 controls growth and invasion in the D492 EMT model, is a marker for oxidative stress, and associated with poor prognosis in claudin-low breast cancer." (PMID 34923141, 2022). "GFPT2 was a marker of poor prognosis in the D492 EMT model of breast cancer, which controlled growth and invasion." (PMID 36276279, 2022). "Bioinformatic and functional analysis revealed that the metabolic enzyme GFPT2 is a marker of claudin-low breast cancer, responds to oxidative stress, and impacts EMT, cell growth, and cell invasion." (PMID 34923141, 2022). "To test the generality of these results, we investigated the expression of GFPT2 across different breast cancer subtypes in both cell lines and patients." (PMID 34923141, 2022). "Gene expression analysis of the cancer genome atlas showed that GFPT2 expression was a characteristic of claudin-low breast cancer." (PMID 34923141, 2022). "KRAS and LKB1 comutant NSCLC emulates claudin-low breast cancer, and GFPT2 was reported in different studies to be the key player in boosting the malignancy of this type of malignant lung cancer." (PMID 34923141, 2022). "The mRNA level of GFPT2 has been up-regulated in many cancers such as glioblastoma, lung adenocarcinoma and breast cancer." (PMID 34737967, 2021). "Collectively, our studies indicate that HAS2 and GFPT2 represent attractive drug targets in human breast cancer." (PMID 32774770, 2020). "In breast cancer, oxidative stress stimulation increases GFPT2 expression." (PMID 38888874, 2024). "Furthermore, in breast cancer, GFPT2 induces EMT by increasing vimentin expression via HBP activation and enhances cell invasion and proliferation." (PMID 38888874, 2024). "The relationship between GFPT2 and breast cancer is largely unknown until a recent study reported that GFPT2 regulates macrophage mitochondrial fission to facilitate the phagocytosis of cancer cells." (PMID 37287069, 2023). "These analyses suggest that GFPT2 is a tumor promoter in claudin-low breast cancer." (PMID 34923141, 2022). "However, it appears that maintenance of GFPT2 expression in claudin-low breast cancer relies on additional factors." (PMID 34923141, 2022). "In addition to affecting the immune microenvironment of pancreatic cancer, GFPT2 has also been reported to be related to the malignant biological behavior of cancer cells in a variety of other cancers including colon cancer, breast cancer and serous ovarian cancer." (PMID 38575607, 2024). "GFPT2 was not positively associated with HER2-positive but rather claudin-low breast cancer." (PMID 34923141, 2022). "Our results indicate that GFPT2 is a claudin-low breast cancer marker, consistent with the previous finding that D492HER2 with higher expression of GFPT2 belongs to the claudin-low breast cell line." (PMID 34923141, 2022). "High expression of GFPT2 is a marker for oxidative stress important for EMT and breast cancer progression." (PMID 34923141, 2022). "GlcNAcylation plays an essential role in breast cancer metastasis and tumorigenesis, in line with the observations that siRNA-mediated knockdown of GFPT2 imparted negative effects on growth and invasion in the mesenchymal cell lines." (PMID 34923141, 2022).
breast carcinoma (continued). "We then used machine learning methods to perform feature selection and reduction, which generated a clinical-friendly scoring system consisting of 5 genes (C3, CD27, GFPT2, GMFG, and HLA-DPB1) that could be used to predict clinical outcomes in breast cancer patients." (PMID 37287069, 2023).
lung carcinoma (9 papers, 2019 to 2025). "The transcription factors Snai1 and Twist1, both working as key regulators of epithelial-mesenchymal transition (EMT), are implicated in upregulating HBP enzymes, especially GFPT2, in KRAS-mutant lung cancer." (PMID 40830088, 2025). "Transcriptomics profiling reveals upregulation of GFPT2 in mesenchymal stem cells within KRAS-driven lung cancer models." (PMID 40830088, 2025). "NF-kB upregulates transcription of GFPT2, which contributes to lung cancer cell migration and invasion." (PMID 35201498, 2021). "For example, SIRT6 downregulates the transcription of GFPT2, which plays a role in lung cancer cell migration and invasion induced by NF-kB." (PMID 35201498, 2021). "Meanwhile, GFPT2 plays a critical role in tumor metabolic reprogramming in lung cancer, acts as a neoplastic marker in tenosynovial giant cell tumors (TGCT), and functions as an androgen receptor-inducible target involved in prostate cancer metabolic reprogramming." (PMID 40830088, 2025). "Recently, the role of GFPT2 in tumorigenesis, such as its association with aggressiveness and EMT/migration, has been gradually recognized in various cancers, including breast, colon, and lung cancer." (PMID 38093368, 2023). "Given that GFPT2 promotes motility of lung cancer cells, we examined whether elevated GFPT2 expression correlated with 5-year overall survival rates in NSCLC." (PMID 30885209, 2019). "The expression of GFPT2, an isoenzyme of GFPT1, is specifically induced in KRAS/LKB1 combined mutant lung cancer cells, and promotes tumorigenicity by enhancing glucose influx into HBP." (PMID 36158580, 2022). "NSCLC tumors exhibit elevated GFPT2 protein expression, linking this metabolic enzyme to EMT and the invasive properties commonly observed in lung carcinomas." (PMID 30885209, 2019). "Modulation of GFPT2 levels alters cell motility and invasion in response to EMT stimuli, affirming its importance in lung cancer progression." (PMID 30885209, 2019).
colorectal cancer (7 papers, 2021 to 2026). A primary or metastatic malignant neoplasm that affects the colon or rectum. "As reported, high GFPT2 expression is associated with poor prognosis in various tumors, including gastric cancer, lung adenocarcinoma and colorectal cancer." (PMID 39834822, 2024). "The expression of GFPT2 in colorectal cancer was shown to be positively correlated with immunosuppressive cells, regulated immunosuppressive factors and T‐cell exhaustion, and increased in tumors." (PMID 40860436, 2025). "GFPT2-induced O-GlcNAcylation has been previously noted to activate NF-κB signaling and establish a positive feedback loop in colorectal cancer." (PMID 40291779, 2025). "GFPT2 was a key enzyme of the hexosamine biosynthesis pathway that was investigated to anticipate the biology of colorectal cancer cells via enhancing the glycosylation of p65 and activating the NF-κB pathway." (PMID 34322485, 2021). "Moreover, it has been reported that GFPT2 is involved in the developing colorectal cancer." (PMID 36686667, 2022).
Insulin resistance (6 papers, 2011 to 2024). Increased resistance towards insulin, that is, diminished effectiveness of insulin in reducing blood glucose levels. "The GFPT2 gene was previously implicated in insulin resistance in type 2 diabetes." (PMID 39438007, 2024). "One such recent study reported hypermethylation and significant correlation of the expression of the GFPT2 gene with enrichment in the insulin resistance and insulin signalling pathways, suggesting that this gene is a suitable candidate biomarker for metabolic syndrome." (PMID 39415250, 2024). "Finally, in metabolism we found concordant upregulation of oxidative stress-response genes such as Gfpt2 and glycolysis related genes such as Pgk1, with downregulation of gluconeogenesis gene Eno2, and diacylglycerol kinases Dgka and Dgkh, important in fatty acid metabolism and insulin resistance." (PMID 21696628, 2011).
lung adenocarcinoma (6 papers, 2021 to 2025). A carcinoma that arises from the lung and is characterized by the presence of malignant glandular epithelial cells. "Overexpression of GFPT2 was previously associated with increased glucose uptake in cancer-associated fibroblasts in lung adenocarcinoma as evaluated by imaging." (PMID 33941787, 2021). "Actually, targeting GFPT2 by azaserine and targeting PGM3 by FR054 can specifically inhibit KRAS/LKB1 combined mutant lung adenocarcinoma cells, respectively." (PMID 36158580, 2022). "In lung adenocarcinoma, GFPT2, but not GFPT1, correlates with poor clinical outcomes; however, GFPT1 is required for glycosylation and high expression of GFPT1 predicts poor prognosis in pancreatic ductal adenocarcinoma." (PMID 40740652, 2025).
non-small cell lung carcinoma (5 papers, 2019 to 2026). A group of at least three distinct histological types of lung cancer, including non-small cell squamous cell carcinoma, adenocarcinoma, and large cell carcinoma. "Similarly, KRAS and LKB1 co-mutations in non-small cell lung cancer (NSCLC) promote GFPT2 expression, which correlates with poor prognosis." (PMID 40830088, 2025). "Moreover, it was also reported that elevated GFPT2 expression was correlated with poor clinical outcome in non-small cell lung cancer." (PMID 35330716, 2022).
type 2 diabetes (5 papers, 2010 to 2024). "Lastly, GFPT2 gene variations (glutamate and /or aspartate mutants) were shown to be associated with type 2 diabetes mellitus." (PMID 37943808, 2023). "Genetic variants in GFPT2 variants are associated with type 2 diabetes and diabetic nephropathy." (PMID 20353610, 2010). "We investigated the association of nine functionally significant polymorphisms in this set of five oxidation pathways modulation genes (ADPRT1, AKR1B1, RAGE, GFPT2 AND PAI-1) with CRI among Asian Indians with type 2 diabetes." (PMID 20353610, 2010). "While there is no direct evidence linking dietary soy, LRRTM4, or GFPT2 with type 2 diabetes risk, the potential for such a connection exists, warranting further investigation." (PMID 39438007, 2024).
diabetes (4 papers, 2010 to 2023). "Allelic and genotypic constitution of 10 polymorphisms (SNPs) from five genes namely- ADPRT1, AKR1B1, RAGE, GFPT2 and PAI-1 with diabetic CRI was investigated." (PMID 20353610, 2010).
pancreatic cancer (4 papers, 2024 to 2025). "GFPT2 is also implicated in stomatin-like protein 1 (STOML1)-driven liver metastasis of pancreatic cancer." (PMID 40830088, 2025). "A recent study demonstrates that gemcitabine administration induces GFPT2 expression and thereby promotes the invasion of pancreatic cancer." (PMID 40830088, 2025). "The CCLE dataset revealed elevated expression of six module genes (GFPT2, MFAP5, CTSK, MMP2, FSTL1, and PRRX1) associated with poor overall survival in patients with pancreatic cancer." (PMID 40430018, 2025). "We observed a positive correlation between GFPT2 and total O-GlcNAcylation in the specimens and validated that GFPT2 promoted O-GlcNAcylation in pancreatic cancer cells." (PMID 38575607, 2024). "Our previous studies revealed a novel link between gemcitabine (GEM) chemotherapy and elevated glutamine-fructose-6-phosphate transaminase 2 (GFPT2) expression in pancreatic cancer (PaCa) cells." (PMID 38888874, 2024). "To further explore the impact of GFPT2 on macrophage polarization, we constructed an in vitro model of pancreatic cancer cells with stable knockdown or overexpression of GFPT2 co-cultured with macrophages." (PMID 38575607, 2024). "First, we detected the expression of GFPT2 in pancreatic cancer cell lines." (PMID 38575607, 2024). "We identified GFPT2, the key enzyme in hexosamine biosynthesis pathway (HBP), as an immune-related prognostic gene in pancreatic cancer using transcriptome sequencing and further confirmed that GFPT2 promoted macrophage M2 polarization and malignant phenotype of pancreatic cancer." (PMID 38575607, 2024). "In conclusion, our study successfully identified a module of six key genes—GFPT2, MFAP5, CTSK, MMP2, FSTL1, and PRRX1—through Weighted Gene Co-expression Network Analysis (WGCNA) to assess cancer-associated fibroblast (CAF) infiltration in pancreatic cancer (PC)." (PMID 40430018, 2025). "However, there are few reports on the effect of GFPT2 on pancreatic cancer cells." (PMID 38575607, 2024). "Utilizing the CCLE database, it was confirmed that fibroblast cell lines exhibited elevated mRNA levels of the six module genes (GFPT2, MFAP5, CTSK, MMP2, FSTL1, and PRRX1) (accessed on 2 March 2025) compared to pancreatic cancer cell lines." (PMID 40430018, 2025). "To further validate the function of GFPT2 in PDAC, we investigated the effects of GFPT2 on the proliferation and migration of pancreatic cancer cells." (PMID 38575607, 2024).
colon adenocarcinoma (3 papers, 2017 to 2023). "In this study, we found that GFPT2 was highly expressed in colon adenocarcinoma and that high expression was associated with poor pathological features and poor clinical prognosis." (PMID 35330716, 2022). "Moreover, increased GFPT2 expression was significantly associated with poorer OS in 329 colon adenocarcinoma (COAD) patients." (PMID 35330716, 2022). "The results showed that high GFPT2 expression was significantly associated with poorer OS in 329 patients with colon adenocarcinoma (COAD) (P=0.028 < 0.05)." (PMID 35330716, 2022). "GFPT2 regulates cell migration and invasion in NSCLC, and its expression is positively correlated with poor survival in patients with serous ovarian cancer, colon adenocarcinoma, and LUAD." (PMID 37430270, 2023).
colon carcinoma (3 papers, 2022 to 2024). "We concluded that GFPT2 expression levels were associated with poor pathological characteristics and poor prognostic features in patients with colon cancer." (PMID 35330716, 2022). "Association between GFPT2 protein expression and clinicopathological characteristics in colon cancer tissues." (PMID 35330716, 2022). "Currently, the specific underlying mechanism between GFPT2 expression and tumor immunity in colon cancer remains unclear, which deserves further investigation." (PMID 35330716, 2022). "However, we will perform some cellular and animal experiments in the future to further confirm whether GFPT2 is associated with colon cancer." (PMID 35330716, 2022). "Overexpression of a protease competing with macrophages for glutamine in colon cancer cells [glutamine-fructose-6-phosphate transaminase 2 (GFPT2)] can impair mitochondrial fission in macrophages, leading to a weakened phagocytic response and drug resistance." (PMID 38302953, 2024). "Such previous findings would indeed agree with the current finding of association between GFPT2 expression and prognosis as well as TME (e.g. CAFs) of colon cancer." (PMID 35330716, 2022). "We next investigated which stromal cell components were the cell subpopulations with high GFPT2 expression in colon cancer." (PMID 35330716, 2022). "By analyzing the KEGG and GO signaling pathways, we found that GFPT2 affects the development of colon cancer mainly through Focal adhesion, and ECM receptor interaction." (PMID 35330716, 2022). "GFPT2 was highly expressed and correlated with poor pathological features in 83 colon cancer patients." (PMID 35330716, 2022). "We collected tissues from 83 colon cancer patients and detected the protein levels of GFPT2 by immunohistochemistry (IHC) assy." (PMID 35330716, 2022). "We further investigated the correlation between the expression levels of GFPT2 and the pathological characteristics of colon cancer patients." (PMID 35330716, 2022). "We examined the protein levels of GFPT2 by immunohistochemistry (IHC) in tissues collected from 83 patients with colon cancer." (PMID 35330716, 2022). "To explore the roles of GFPT2 in patients with colon cancer, we first investigated the expression levels of GFPT2 in colon cancer." (PMID 35330716, 2022). "High levels of protein expression of GFPT2 were positively correlated with unfavorable clinicopathological features in 83 samples of colon cancer patients." (PMID 35330716, 2022). "To further explore the relationship between GFPT2 expression and prognosis of colon cancer patients, we investigated the overall survival (OS) of GFPT2 in the TCGA database using Kaplan-Meier." (PMID 35330716, 2022). "Here, GFPT2 expression was highly correlated with EMT-related factors, indicating that GFPT2 might be capable of regulating the promotion of colon cancer metastasis." (PMID 35330716, 2022). "In this study, we found that GFPT2 and colon cancer are closely related, and we identified the value of GFPT2 in patient prognosis prediction, tumor microenvironment, tumor immunity and drug sensitivity through the analysis of TCGA database and validation of clinical samples." (PMID 35330716, 2022). "However, the potential roles of GFPT2 in colon cancer still need to be fully investigated." (PMID 35330716, 2022). "We explored a colon cancer single cell GSE dataset (GSC_GSE146771_Smartseq2) and found that GFPT2 was expressed in both immune and stromal cell single cell subpopulations." (PMID 35330716, 2022).